RRM2 (ribonucleotide reductase regulatory subunit M2)
Diseases named in the same sentence as RRM2 in open-access papers (continued):
Sharing a sentence is not in itself a finding about the gene and the disease.
tumor (continued). "Therefore, we adopted a spheroid-based functional assay to investigate the effect of downregulation of RRM2 or VEGF on tumor cell migration." (PMID 34683911, 2021). "RRM2 as a tumor driver is frequently overexpressed in various malignancies." (PMID 34384030, 2021). "RRM2 is overexpressed in cancer and promotes tumor progression." (PMID 34094915, 2021). "Indeed, knockdown of RRM2 was accompanied by RRM2 protein level decrease in tumor cells after PF6/siRRM2 treatment compared to untreated (UT) cells." (PMID 34683911, 2021). "The qRT-PCR results showed that CCNB1, CDK1, and RRM2 were significantly upregulated in liver cancer tumor samples (P < 0.0001) and cell lines (P < 0.05) compared with the relevant adjacent non-tumor liver tissues and normal liver cell LO2." (PMID 33685467, 2021). "The knockdown of RRM2 significantly suppressed the tumorigenesis of Y79 cells in nude mice, as revealed by the suppressed tumor volume increase and the reduced tumor weight." (PMID 34895038, 2021). "The tumor size in the RRM2 silencing group were lower than that in the NC group." (PMID 33858512, 2021). "Knockdown of RRM2 suppressed tumor growth in the xenograft tumor models." (PMID 33858512, 2021). "Additionally, the multivariate Cox analyses confirmed the critical value of T classification and RRM2, proving that they can predict tumor prognosis independently of other factors in overall survival." (PMID 33123291, 2020). "Since we observed a slightly higher tumor incidence in Chk1 and Rrm2 transgenic mice, these mice could possibly survive longer in a cancer-resistant background." (PMID 32253367, 2020). "RRM2 functions as a tumor driver is frequently overexpressed in various malignancies." (PMID 33411689, 2020). "Moreover, we checked the Oncomine online database finding that many datasets suggested that the mRNA expression of RRM2 increased in tumor tissues." (PMID 33123291, 2020). "Several potent inhibitors for RRM2 protein have been described that suppress tumor growth." (PMID 32284791, 2020). "Delivery of RRM2 siRNA alone or in combination with adriamycin could inhibit xenografted or orthotopic tumor growth established in nude mice." (PMID 31936661, 2020). "In addition, miRNA 99a-3p had a tumor-suppressive role through regulating ribonucleotide reductase regulatory subunit-M2 (RRM2) in sunitinib-resistant RCC cells." (PMID 32379831, 2020). "Furthermore, 11 genes in the RRM2 signature were correlated with enzalutamide resistance by using a single-cell RNA-seq dataset from PC circulating tumor cells." (PMID 32385899, 2020). "RRM2 was highly expressed as tumor stage increased (p-value = 1.991e-05)." (PMID 33123291, 2020). "A higher expression of RRM2 was related to a higher tumor stage." (PMID 33123291, 2020). "The distribution of RRM2 showed a significant difference among the tumor stages." (PMID 33123291, 2020). "RRM2 is upregulated in tumor stage MF and its downregulation by S4+S5 is an interesting observation as RRM2 may be a relevant target for S4+S5 treatment." (PMID 32284791, 2020). "Moreover, using multidimensional analysis, we assessed the co-expression and functional network associated with RRM2 in LUAD and studied its part in tumor immunity." (PMID 33123291, 2020). "In addition to MCM2-7 complex, other proteins in the cluster also influenced the growth and division of tumor cells by participating in the cell cycle such as RRM2, PRKAR2B, and MKI67." (PMID 33200655, 2020). "In addition to participating in DNA synthesis, RRM2 also has an impact on the potential biological behavior and metastasis of malignant tumors and the generation of tumor drug resistance." (PMID 31673243, 2019). "The observed higher levels of Sirt2 could potentially deacetylate RRM2 to increase RNR activity in tumor tissues." (PMID 31324785, 2019).
tumor (continued). "It targets and inhibits RRM2, the enzyme involved in the critical conversion of ribonucleotides to deoxyribonucleotides, essential in DNA replication and one of the most expressed enzymes in tumor cells." (PMID 31480699, 2019). "However, these levels were able to inhibit tumor growth in subcutaneous transplanted tumor when combined with RRM2 gene therapy." (PMID 31673243, 2019). "Over expression of RRM2 plays a positive role in tumor growth." (PMID 31673243, 2019). "In addition, the patients also showed inhibition of tumor growth, as siRNA treatment was able to reduce the expression of the M2 subunit of RRM2." (PMID 31064156, 2019). "RRM2 is frequently overexpressed in various malignancies and functions like a tumor driver." (PMID 30898978, 2019). "In conclusion, the new chimeric transcript RRM2-c2orf48 in NPC cells and tissues may be associated with tumor development." (PMID 28906488, 2017). "In this study, to explore the potential role for mTOR signaling in the regulation of RNR in cancer cells, we have determined the mRNA and protein levels of RRM1 and RRM2 in cell culture and mouse tumor xenografts following pharmacological and genetic inhibition of mTOR signaling." (PMID 28507282, 2017). "We detected high RRM2 expression in tumor tissue as well as normal bladder." (PMID 28289079, 2017). "Both, BRCA1 and RRM2 mRNA levels were significantly higher in HGG (WHO grade III+IV) compared with LGG (WHO grade II), whereas the RRM2 expression was also significantly higher in WHO grade IV tumours compared with WHO grade III, thereby supporting our findings above." (PMID 27845331, 2016). "Our previous work has reported that RRM2 contributes to tumor invasion and metastasis in CRC." (PMID 27801665, 2016). "Besides, some evidences suggest that RRM2 can enhance tumor angiogenesis by decreasing thrombspondin-1 and increasing VEGF production." (PMID 27801665, 2016). "Next, the tumor samples were stained with anti-RRM2 and -Ki67 antibodies, respectively." (PMID 26675256, 2016). "The percentage of anti-RRM2 positive cells per 500 cells in 2 tumor samples was enumerated." (PMID 26675256, 2016). "A central role for inhibition of HDAC activity by ABC294640 resulting in multifaceted, but complimentary, downstream modulation of c-Myc, p21, phospho-Rb and RRM2 expression all combine to attenuate tumor cell proliferation and increase sensitivity to gemcitabine." (PMID 27517489, 2016). "Overexpression of RRM2 expands the dNTP pool and confers gemcitabine resistance to tumor cells." (PMID 25946136, 2015). "RRM2 may interact with a variety of oncogenes that promote tumor progression and enhance the invasiveness of cancer cells." (PMID 24637958, 2014). "In searching for putative miRNA inhibitors of RRM2 by computational miRNA target prediction algorithms, we found the let-7 family of tumor suppressor miRNAs to possess a seed match for base pairing with the 3′ UTR of RRM2 (context score percentile: 94; TargetScanHuman 5.1)." (PMID 23335963, 2013). "Together our data, with previous studies, suggest that inhibiting RRM2 may have anti-angiogenic and anti-tumour effects." (PMID 23056178, 2012). "Indeed we have shown that out of the endothelial enriched genes, Smurf2, Hex-B, Atf1, and Nras, plus Rrm2, which has known roles in tumour biology, that depletion of Rrm2, Atf1 and Hex-B have anti-angiogenic consequences in ex vivo mouse aortic ring assays." (PMID 23056178, 2012). "Apart from the well-known role in ribonucleotide reduction, several studies have indicated that RRM1 and RRM2 may play opposite roles in controlling malignant progression of tumor cells." (PMID 19250552, 2009). "Next, we assessed the effect of RRM2 on tumor in vivo growth." (PMID 19250552, 2009). "In addition to its essential role in ribonucleotide reduction, ribonucleotide reductase (RNR) small subunit, RRM2, has been known to play a critical role in determining tumor malignancy." (PMID 19250552, 2009).
tumor (continued). "Therefore, in the present study, we examined the impact of the RRM2 on tumor angiogenesis through its regulating the expression of proangiogenic factor VEGF, and antiangiogenic factor TSP-1." (PMID 19250552, 2009). "Overexpression of RRM2 significantly enhances the invasive and metastatic potential of tumor." (PMID 19250552, 2009). "To answer whether overexpression of RRM2 had a positive effect on tumor angiogenesis, we firstly determined the effect of overexpression of RRM2 on the production of well known pro- and anti-angiogenic factors." (PMID 19250552, 2009). "Our results indicate a positive role of RRM2 in tumor angiogenesis and progression." (PMID 19250552, 2009). "In this study, we therefore focused on the effect of RRM2 on tumor angiogenesis." (PMID 19250552, 2009). "In addition, prospective studies using gemcitabine, either as a single agent or in combination with other drugs, are warranted to further clarify the relation between RRM1 and RRM2 coexpression and tumour chemosensitivity." (PMID 18414411, 2008). "m6A-modulated mRNA stability, particularly via IGF2BP1, regulates the expression of RRM2 and thrombospondin 1 (THBS1), contributing to resistance against ferroptosis and the glycolytic reprogramming of tumor-associated macrophages, ultimately promoting tumor progression and fibrosis." (PMID 41376856, 2026). "The aberrant expression of RRM2 and ADH1B across all 13 cancer types prompted us to explore whether they can server as pan-cancer diagnostic markers to distinguish between normal and tumor samples." (PMID 39884577, 2025). "Therefore, we speculated that TFRC may play an important role in regulating the biological functions of tumor cells by modulating iron uptake and affecting the activity of RRM2." (PMID 40510157, 2025). "Furthermore, a positive correlation was found between HCG18 or RRM2 expression and tumor stage." (PMID 40303288, 2025). "Additionally, RRM2 expression was significantly associated with both tumor grade and stage in LIHC, suggesting that RRM2 may be involved in tumor progression and aggressiveness." (PMID 40493217, 2025). "Similarly, RRM2 expression increased as tumor grade increased." (PMID 39256879, 2024). "Moreover, miR-20a-5p inhibited tumor angiogenesis of NSCLC through RRM2/PI3K/Akt signaling pathway." (PMID 38820515, 2024). "Furthermore, RRM2 has been identified as a tumor promoter and cancer therapeutic target." (PMID 36768940, 2023). "Therefore, we investigated the expression level of RRM2 in tumor and normal liver tissues based on The Cancer Genome Atlas (TCGA) database, and through bioinformatics analysis to verify whether RRM2 could be used as a meaningful biomarker in HCC." (PMID 37056349, 2023). "Results indicate that RRM2 was significantly overrepresented in immune-related pathways, specially, immunoregulatory interactions between lymphoid and non-lymphoid cell pathways are a notable immune-related pathway that modify the response of lymphoid cells to self, tumor, and pathogen antigens." (PMID 36518297, 2022). "In addition, high RRM2 expression may contribute to the tumor immune microenvironment, suggesting that the carcinogenic effect of RRM2 may be realized through the regulation of immune-related genes." (PMID 36518297, 2022). "This article suggested that RRM2 may influence TME to regulate tumor progression." (PMID 35740608, 2022). "Moreover, RRM2 silencing inhibited the progression of various tumor cells." (PMID 36678539, 2022). "In addition, RRM2 may directly or indirectly contribute to macrophage polarization and tumor immune evasion in BLCA, COAD, ESCA, KIRP, PAAD, and STAD." (PMID 36518297, 2022). "Likewise, PFS and DFS analysis also showed that RRM2 was an unfavorable factor for tumor patients." (PMID 35740608, 2022). "Additionally, it has been reported that RRM2 can affect the proliferation of tumor cells." (PMID 35204799, 2022).
tumor (continued). "Thus, our study provided significant insights into the potential role of RRM2 in tumor immunology." (PMID 36202136, 2022). "Our findings showed that the high expression of RRM2 in HCC was closely related to PD1, PD-L1, and CTLA-4, suggesting that tumor immune escape may be involved in RRM2-mediated hepatocarcinogenesis, and RRM2 may be a synergistic therapeutic target related to immunotherapy in HCC." (PMID 35911380, 2022). "Also, we compared the RRM2 methylation of different types of tumor tissues with normal ones." (PMID 36202136, 2022). "Moreover, to confirm the anti-tumor effects of RRM2 silencing were mainly due to cGAS/STING pathway mediated CD8 + T cells infiltrations in vivo, T cells depletion by monoclonal antibody treatment could be a better choice." (PMID 33858512, 2021). "Finally, in our ACC cohort, patients with high RRM2 expression levels at the tumor level showed a strong tendency towards poorer overall survival compared to the others (median survival 36 vs. 124 months, p = 0.05, HR 5.11, 95%CI 1.26–20.82), while no such effect was detectable for RRM1 (p = 0.177)." (PMID 34439352, 2021). "However, Rrm1 and Rrm2 are overexpressed in various malignant tumors, acting as tumor drivers." (PMID 33679891, 2021). "Therefore, in the future, it would be interesting to design anti-BRCA strategies by counterbalancing the activities of E2 and E3 ligases, for example, to maintain CCNF to suppress tumor-promoter RRM2 and/or inhibit FBXL8 and FZR1 to reduce their targeting of tumor-suppressor CCNF protein." (PMID 34201347, 2021). "RRM2 could be a promising target for tumor regression through cancer immunotherapy in LUAD." (PMID 33858512, 2021). "Hence, these data indicate that RRM2 independent role of ANXA1 may also be important for RCC tumor growth." (PMID 34319001, 2021). "Furthermore, the increased tumor incidence in Chk1 and Rrm2 transgenic mice could affect their survival, as is the case for TERT-overexpressing mice." (PMID 32253367, 2020). "Besides, we found that the copy number of RRM2 also increased in tumor tissue." (PMID 33123291, 2020). "Moreover, RRM2 became increased expression in patients with tumor metastasis (p-value = 0.018)." (PMID 33123291, 2020). "Therefore, the expression level and activity of RRM2 are closely related to the proliferation of tumor cells and may play a decisive role in the mechanism of controlling the invasion and development of malignant tumors." (PMID 31673243, 2019). "Importantly, RRM2 functions as a driver in a variety of tumors, with in vivo and in vitro experiments confirming that knocking down expression using siRNA significantly inhibits tumor cell proliferation." (PMID 30778371, 2019). "Such an RRM2-c2orf48-mediated mechanism may enhance heterotypic signals induced by extrinsic stimuli to in turn induce the acquisition of mesenchymal traits by cancer cells and to promote metastasis during later stages of tumor progression." (PMID 28906488, 2017). "Therefore, patients with tumour cells overexpressing RRM2 may more easily progress, thus supporting our finding that RRM2 expression levels may be a valuable indicator of prognosis." (PMID 26663950, 2015). "It is important to investigate whether the angiogenic potential of tumor is affected by RRM2." (PMID 19250552, 2009). "Recent studies have further elucidated that RRM2 contributes to resistance against docetaxel chemotherapy by stabilizing ANXA1 and activating the PI3K/AKT signaling pathway, thereby enhancing tumor cell survival under chemotherapeutic stress." (PMID 41346575, 2025). "Among these, seven genes, namely, RRM2, KIF11, ANLN, CDC20, YWHAZ, DTL, and PCNA, exhibited significantly elevated expression in tumor samples (p ≤ 0.05)." (PMID 41487287, 2025). "The present study provides a comprehensive analysis of the role of RRM2 in LUAD and its interplay with miRNAs and the tumor immune microenvironment." (PMID 41357570, 2025).
tumor (continued). "Further RRM2, GMPS, BCAT1, PYCR2, and NEU1 are identified in tumor tissue as actionable candidates for prevention." (PMID 40290517, 2025). "When analyzed according to MSI and MSS status, adjusted for tumor location (right vs. left), BUB3, CDKN1A (p21), and RRM2 were significantly more upregulated in MSI tumors than in MSS tumors." (PMID 41440189, 2025). "Through Western blot experiments, we foundthat increased RRM2 expression significantly elevated the expressionof cell cycle- and DNA damage repair-related proteins, such as cyclinB1 and CHEK1, in both tumor cells and HVECs." (PMID 40834268, 2025). "Through its role as a transcriptional coactivator of RRM2, high expression of BRCA1 may mask its functional defects, leading to inefficient DNA damage repair, thereby promoting genetic mutations and instability in tumor cells and accelerating tumor progression." (PMID 41497799, 2025). "Combinatorial therapies also show promise: osalmid, targeting RRM2 to induce senescence, synergizes with the senolytic navitoclax to exploit BCLXL dependence, effectively reducing tumor growth in preclinical models." (PMID 40781676, 2025). "Inhibition of HCG18 or RRM2, or activation of miR-30a-5p significantly decreased the tumor growth, but markedly increased the Fe2+ and MDA induced by erastin in tumor tissues." (PMID 40303288, 2025). "Targeted interventions, such as modulating RRM2, TS, and other key enzymes or disrupting the PI3K/AKT/mTOR pathway, have demonstrated potential in reducing tumor growth and inflammation in pancreatic tissue." (PMID 41200180, 2025). "By inhibiting RRM2, microRNA-20a-5p disrupts the activation of the PI3K/Akt pathway, which is crucial for promoting angiogenesis and tumor growth." (PMID 40014586, 2025). "In terms of the molecular mechanism, lncOCMRL1 binds the proto-oncoprotein RRM2 to maintain its stability and promotes EMT in tumor cells, thereby inducing tumor metastasis and growth." (PMID 39343925, 2024). "While PBK, RRM2, and DLGAP5 contribute to tumor biology, their roles in genomic stability and mismatch repair are less direct, making them less immediate research priorities in this context." (PMID 39777332, 2024). "RRM2 promotes EMT and promotes the invasive phenotype of tumor cells by activating the JAK2-STAT3 pathway." (PMID 39343925, 2024). "(iii) responding to the high concentration of GSH in tumor cells, leading to the rapid release of siOCMRL1, silencing siOCMRL1 and blocking the RRM2/EMT signaling pathway, thereby achieving the effect of inhibiting tumor growth and metastasis." (PMID 39343925, 2024). "Overall, these findings suggested that RRM2, SLC2A1, DDIT4, and VDAC2 were potential oncogene, whereas PEBP1 and IL33 were candidate tumor suppressor genes." (PMID 39311766, 2024). "As we expected, RRM2, SLC2A1, DDIT4, and VDAC2 were significantly upregulated transcriptionally and translationally in tumor samples, whereas PEBP1 and IL33 are significantly reduced in tumorous tissues." (PMID 39311766, 2024). "The expression of RRM2 in iCCA patients was evaluated with immunohistochemistry (IHC) in iCCA cohort 4, which included 31 paired FFPE iCCA tumors and adjacent non-tumor FFPE liver tissues." (PMID 39243109, 2024). "The elevated expression of RRM2 in HCC was significantly correlated with T stage (P <0.05), pathologic stage (P <0.05), tumor status (P <0.05), histologic grade (P<0.001), and AFP (P <0.001)." (PMID 37056349, 2023). "Further study found that the reduction in RRM2 gene expression was found to be directly correlated with a decrease in AKT phosphorylation levels, ultimately leading to a heightened anti-tumor effect of docetaxel." (PMID 37968699, 2023). "To determine if the RNR M2 subunit switching we observed in vitro occurred in vivo, we collected HB214 tumors two days and 34 days post irinotecan treatment and performed RRM2 and RRM2B RNAscope staining on tumor sections." (PMID 36882565, 2023).